LRPAP1 (LDL receptor related protein associated protein 1)
Description:
Molecular chaperone for LDL receptor-related proteins that may regulate their ligand binding activity along the secretory pathway.
Synonyms: Alpha-2-MRAP; RAP; A2MRAP; HBP44; A2RAP; MYP23
Tractability: Antibody: UniProt places it where antibodies can reach, with high confidence; its Gene Ontology location is reachable by antibodies, with high confidence; UniProt predicts a signal peptide or a membrane-spanning region. PROTAC: ubiquitination databases record sites on it; its protein half-life has been measured.
Gene: Protein-coding gene on chromosome 4 (3,503,612 to 3,532,446, reverse strand). Ensembl gene ENSG00000163956.
Subcellular location: Rough endoplasmic reticulum lumen; Endoplasmic reticulum-Golgi intermediate compartment lumen; Golgi apparatus, cis- Golgi network; Golgi apparatus lumen; Endosome lumen; Cell surface
Subcellular location (Human Protein Atlas): Endoplasmic reticulum
Gene Ontology:
Molecular function: low-density lipoprotein particle receptor binding; protein binding; receptor antagonist activity; receptor ligand activity; very-low-density lipoprotein particle receptor binding; amyloid-beta binding; lipase binding; signaling receptor binding; heparin binding
Biological process: amyloid-beta clearance by transcytosis; negative regulation of amyloid-beta clearance; negative regulation of receptor internalization; negative regulation of very-low-density lipoprotein particle clearance; regulation of receptor-mediated endocytosis; signal transduction; extracellular negative regulation of signal transduction; positive regulation of amyloid-beta clearance
Cellular component: cell surface; cis-Golgi network; endoplasmic reticulum; endoplasmic reticulum-Golgi intermediate compartment; endosome; endosome lumen; Golgi apparatus; Golgi lumen; plasma membrane; rough endoplasmic reticulum lumen; endomembrane system; extracellular region; vesicle
Genetic constraint (gnomAD): Loss-of-function variants: 41 observed, 38.69 expected, observed/expected ratio (o/e) 1.06, 90% interval 0.82 to 1.38. The synonymous counts are far from expectation, so gnomAD's model fits this gene poorly and the ratio says little. Missense variants: 565 observed, 475.33 expected, observed/expected ratio (o/e) 1.19, 90% interval 1.11 to 1.27. Synonymous variants: 263 observed, 208.59 expected, observed/expected ratio (o/e) 1.26, 90% interval 1.14 to 1.4.
Homologues: Orthologues: chimpanzee LRPAP1 (99% identical), macaque LRPAP1 (96% identical), dog LRPAP1 (78% identical), mouse Lrpap1 (76% identical), rat Lrpap1 (76% identical), guinea pig LRPAP1 (75% identical), pig LRPAP1 (74% identical), tropical clawed frog lrpap1 (62% identical), zebrafish lrpap1 (54% identical), Drosophila melanogaster CG8507 (32% identical), Caenorhabditis elegans C15C8.4 (25% identical).